NRP1 (neuropilin 1)
Diseases named in the same sentence as NRP1 in open-access papers (continued):
Sharing a sentence is not in itself a finding about the gene and the disease.
breast carcinoma (continued). "Since the ectopic overexpression of NRP-1 in BT-474 breast cancer cells was associated with the upregulation of tenascin C (TN-C), we next explored this relationship in MDA -231, NRP-1 KO, and NRP-1 Rescue cells using immunofluorescence staining (upper left)." (PMID 37175499, 2023). "NRP1 acts as an oncogene and is involved in the progression of cancer, including breast cancer, lung cancer, bladder cancer, and renal cell carcinoma." (PMID 36841806, 2023). "NRP1 is involved in regulating the occurrence, drug resistance and metastasis of bladder cancer, lung cancer, stomach cancer, breast cancer, ovarian cancer and other cancers." (PMID 37702613, 2023). "Experimental studies have proven that FOXO3a interacts with the miR-29b/miR-338 promoter to inhibit breast cancer cell proliferation, while miR-29b and miR-338 target the 3’-UTR of VEGF-A and NRP1, respectively, to oppress breast cancer cell growth." (PMID 37965449, 2023). "VEGF-A/NRP1 axis was suggested to confer cancer stem cell traits in MDA-MB-231 breast cancer cells by activating the Wnt/β-catenin pathway." (PMID 38239643, 2023). "NRP1, a transmembrane glycoprotein, contributes to stemness and radioresistance of breast cancer through WTAP-mediated m6A methylation of Bcl-2 mRNA." (PMID 37598390, 2023). "Our previous studies indicated that knockdown of NRP-1 blocks cell proliferation, metastasis, stemness, and promotes cell apoptosis in breast cancer." (PMID 34374639, 2022). "We define distinct phenotypes of NRP2 isoform-expressing TAMs in mouse models of breast cancer and within malignant pleural effusions from breast cancer patients which were exclusive of neuropilin-1 expression." (PMID 35651620, 2022). "Previously, we reported that NRP-1 was frequently upregulated in breast cancer and functioned as an oncogene to accelerate tumorigenesis and progression by promoting proliferation, metastasis, and stemness." (PMID 34374639, 2022). "In a model of breast cancer, the same investigators examine Nrp1 levels during chemotherapy: in response to the human epidermal growth factor receptor 2 (HER2) inhibition with trastuzumab Nrp1 was increased." (PMID 36203599, 2022). "Small peptides that inhibit VEGF‐A165 binding to NRP‐1 hamper tumour growth and angiogenesis in breast cancer and lung carcinoma animal models." (PMID 34252269, 2022). "Collectively, our data strongly support the claim that RP11-70C1.3 positively regulates breast cancer chemoresistance through miR-6736-3p/NRP-1 axis." (PMID 34374639, 2022). "High-dimensional single-cell analysis identified unique TAM subsets in both murine mammary tumors and human malignant pleural effusions (MPEs) from breast cancer patients that were distinct from NRP1-expressing TAMs." (PMID 35651620, 2022). "Increased serum levels of VEGF and PDGF-CC and decreased levels of HB-EGF and NRP-1 were observed in breast cancer patients when compared to the control group." (PMID 35887839, 2022). "In Michigan Cancer Foundation-7 (MCF-7) breast cancer cells, Nrp1-VEGF-A signals through wingless/integrated protein (Wnt)/β-catenin pathways, to confer stemness and chemoresistance." (PMID 36203599, 2022). "In conclusion, our study indicated that lncRNA RP11-70C1.3 regulated NRP-1 expression by sponging miR-6736-3p to confer chemoresistance of breast cancer cells." (PMID 34374639, 2022). "The present analysis focuses on the serum protein levels of VEGF, PDGF-CC, HB-EGF and NRP-1 in women diagnosed with breast cancer, in comparison with healthy women." (PMID 35887839, 2022). "Consistent with the previous studies, we observed an increased expression of NRP-1 in breast cancer chemoresistant tissues and cell lines." (PMID 34374639, 2022). "NRP1 has been reported to be an oncogene by participating in the development and progression of cancers, such as lung adenocarcinoma, breast cancer, prostate cancer, and gastric cancer." (PMID 36523987, 2022).
breast carcinoma (continued). "Pearson correlation analysis also showed that RP11-70C1.3 had a significantly positive correlation with NRP-1 in breast cancer tissues." (PMID 34374639, 2022). "Taken together, our data support an unequivocal role for RP11-70C1.3/miR-6736-3p/NRP-1 axis in the development of breast cancer chemoresistance." (PMID 34374639, 2022). "Our findings identify NRP1 over-expression as a feature of claudin-low breast cancers, a substantial proportion of TNBC." (PMID 35078508, 2022). "More importantly, rescue experiments showed that NRP-1 overexpression reversed the inhibitory effects of RP11-70C1.3 knockdown on breast cancer cell chemoresistance." (PMID 34374639, 2022). "Clinically, our results show that the FOXO3a-miR-29b-2/miR-338-VEGF-A/NRP1 axis is dysregulated and plays a critical role in disease progression in breast cancer." (PMID 33262463, 2021). "We observed a significant inverse correlation between FOXO3a and VEGF-A/NRP1 expression levels, and a significant positive correlation between VEGF-A and NRP1 in the breast cancer tissue set." (PMID 33262463, 2021). "The results suggested that NRP-1 was highly expressed in malignant melanoma, breast cancer, liver cancer, and colon cancer." (PMID 34616773, 2021). "Here, we report that FOXO3a is functionally related to the inhibition of VEGF-A/NRP1 signaling and to the consequent suppression of breast cancer metastasis." (PMID 33262463, 2021). "The role of mdig on NRP1 was also confirmed in both MDA-MB-231 breast cancer cells and A549 lung cancer cells." (PMID 34335974, 2021). "Co-culture of hBCF6008 human breast cancer CAFs and MCF10CA1a cells, which express high levels of αv integrins and low to moderate levels of NRP-1 led to the formation of stromal networks in between tumor cell nests." (PMID 33750829, 2021). "It has been reported that the expression level of NRP-1 correlates with lymph metastasis and inversely correlates with the survival in breast cancer." (PMID 33912463, 2021). "Several studies have shown that NRP1 is expressed in tumor cells of many cancers, such as breast cancers, lung cancers, pancreatic cancers, oral cancers, or brain tumors, such as gliomas and medulloblastomas." (PMID 34277411, 2021). "Our study reveals a novel mechanistic insight for breast cancer metastasis mediated by the FOXO3a-miRNA-VEGF/NRP1 signaling axis and highlights the potential of targeting FOXO3a-miR-29b/miR-338 as a novel therapeutic strategy for breast cancer." (PMID 33262463, 2021). "Neuropilin-1 (NRP-1) is highly expressed in multiple tumors, including breast cancer, prostate cancer, colon cancer and glioma." (PMID 34261493, 2021). "Using a Neuropilin-1 transmembrane domain interfering peptide, the proliferation of BC cell lines was inhibited and tumor size was reduced in murine models of breast cancer." (PMID 33884469, 2021). "Taken together, our findings suggested that FOXO3a-miRNA-VEGF-A/NRP1 signaling is dysregulated and plays a critical role in disease progression of breast cancer." (PMID 33262463, 2021). "We next analyzed the correlation of FOXO3a, VEGF-A, and NRP1 expression with the prognosis of breast cancer patients with lymph node metastasis in the cases from the Kaplan–Meier plotter data set." (PMID 33262463, 2021). "Taken together, these findings indicated that FOXO3a negatively regulates VEGF-A/NRP1 and that dysregulated FOXO3a/VEGF-A/NRP1 signaling plays a critical role in disease progression in breast cancer." (PMID 33262463, 2021). "NRP-1 is shown to contribute to the metastasis of breast cancer, and its expression level correlates inversely with the survival of breast cancer patients." (PMID 33912463, 2021). "All these studies highlight the significance and importance of NRP-1 in breast cancer, particularly, TNBC." (PMID 33912463, 2021). "To do this, we analyzed the molecular taxonomy of breast cancer international consortium (METABRIC) dataset for transcriptional regulators that correlated with NRP1 expression." (PMID 33128042, 2021).
breast carcinoma (continued). "Whereas CL-14 already has been described to be permissive in a preprint, the breast carcinoma cell line CAL-51 with high levels of NRP1 beside ACE2 and TMPRSS2 expression and the colon carcinoma cell line CL-40 have not been identified before." (PMID 34339474, 2021). "NRP-1 is found to be overexpressed in many tumors, including breast cancer, melanoma, and glioblastoma, indicating that NRP-1 plays a critical role in tumor progression." (PMID 32847045, 2020). "Down-regulation of VEGF and NRP1 in MDA-MB-231 cells and overexpression of VEGF and NRP1 in MCF-7 cells confirmed that the VEGF/NRP1 signaling pathway is instrumental in driving stemness properties of breast cancer cells." (PMID 32766254, 2020). "In breast cancer, PlGF1 and NRP1 overexpression is correlated to a poor prognosis and PlGF2 is overexpressed in cancer tissues as compared to normal tissue." (PMID 32766254, 2020). "Neuropilin 1 is expressed on breast cancer cells, and its interaction with VEGF165 inhibits apoptosis." (PMID 32766254, 2020). "Intriguingly, anti-NRP1 monoclonal antibody treatment repressed adhesion of MCF7 breast cancer cells." (PMID 32508529, 2020). "In breast cancer cells, TGFβ levels as well as the downstream expression of NRP1 and SMAD-2 are negatively regulated by microRNA (miR)-206, and overexpression of miR-206 inhibits EMT as well as migration and invasion of breast cancer cells." (PMID 30717262, 2019). "VEGF also stimulates the migration of breast cancer by forming filopodia via the neuropilin-1 (NRP1)/ARHGAP17/Cdc42, signaling pathway." (PMID 31500658, 2019). "In a recent paper, the authors explored the involvement of NRP1 in doxorubicin sensitivity of breast cancer cells; they showed that the VEGF-A/NRP1 axis promoted cancer stem cells (CSCs) self-renewal via the Wnt/β-catenin pathway." (PMID 31027288, 2019). "Paired t-test analysis of 22 locally advanced breast cancer patients showed that plasma NRP-1 levels were increased significantly (p = 0.018) post-NAC in patients with pathological partial response (pPR)." (PMID 31106153, 2019). "There is also suggestive evidence that VEGF/NRP1 signaling confers CSC properties in breast cancer by activating Wnt/β-catenin signaling." (PMID 30678134, 2019). "Previously, we showed that systemic levels of neuropilin-1 (NRP-1) and its associated molecules correlated with poor-prognosis breast cancer." (PMID 31106153, 2019). "In breast cancer, NRP1/VEGF-A signaling promotes a CSC phenotype and the formation of aggressive and highly vascularized tumors by activating the Wnt/β-catenin pathway." (PMID 30717262, 2019). "Targeting the transmembrane domain of NRP1, a peptide corresponding to the NRP1 transmembrane domain, termed pTM-NRP1, shows antiangiogenic activity in a xenograft mouse model of glioma and inhibits breast cancer growth and metastasis." (PMID 30717262, 2019). "In most renal cell carcinomas, sarcomas, lung adenocarcinomas and various additional tumors, NRP1 levels were significantly increased in tumor versus normal tissue, in contrast to reduced expression in certain other tumors e.g. breast cancer versus normal." (PMID 31208428, 2019). "In summary, we indicate for the first time the global transcriptomic changes triggered by NRP-1 overexpression in breast cancer." (PMID 29728077, 2018). "Our study in the BT-474 breast cancer model provides further insight into this pathway by highlighting the role of NRP-1 in triggering ITGB3/FAK/Akt-473 in a TNC-dependent pathway to trigger cell migration." (PMID 29728077, 2018). "Overexpression of NRP1 in renal or breast cancer cells enhances the Ras/ERK signaling, and that in pancreatic cancer cells induces chemoresistance." (PMID 29659486, 2018). "In order to understand the functional role of NRP-1 in breast cancer progression, NRP-1 was stably overexpressed in the BT-474 cell line, which has very low baseline levels of NRP-1 compared to other breast cancer cell lines such as MDA-MB-231 and MCF-7." (PMID 29728077, 2018).
breast carcinoma (continued). "Most recently, we reported upregulated plasma and tumor tissue expression of NRP-1 in breast cancer cases with advanced nodal and metastatic disease, and particularly in triple negative breast cancer compared to other molecular subtypes." (PMID 29728077, 2018). "The role of NRP-1 in triggering tumorigenic behavior has been indicated in several cancer types, including breast cancer." (PMID 29728077, 2018). "A trend towards a better response to bevacizumab was also observed in breast cancer tumors with low NRP1 expression." (PMID 30027561, 2018). "The expression of NRP-1 in PBMCs decreased similarly in both early onset breast cancer cases and older cases compared to their respective age-matched controls." (PMID 28607365, 2017). "Breast cancer patients displayed significantly decreased expression of NRP-1 (p < 0.0001), SNAI1 (p < 0.0001) and SEMA4A (p < 0.0001) in PBMCS compared to healthy controls." (PMID 28607365, 2017). "Extrapolating from these observations, NRP-1 tumor tissue expression was also upregulated in Stage 4 (n = 15) compared to Stage 3 (n = 38, p = 0.012) breast cancer cases." (PMID 28607365, 2017). "Plasma levels of both NRP-1 and PlGF were quantified in healthy controls and breast cancer patients and correlated to patient disease characteristics." (PMID 28607365, 2017). "Results presented in this study reinforce the connection of Wnt/β-catenin signaling and the function of MaSC, providing new insight into targeting stem cells in breast cancer through antagonizing Nrp1." (PMID 28887477, 2017). "Older breast cancer patients compared to early onset patients presented with higher plasma levels of both NRP-1 and PlGF." (PMID 28607365, 2017). "Our data demonstrate that Nrp1 is critical for mammary development and tumorigenesis, revealing new insights into MaSC regulation and targeting stem cells in treatment of breast cancer." (PMID 28887477, 2017). "To address this need, we tested a novel strategy inhibiting the recently identified breast cancer target neuropilin-1 (NRP1), a membrane receptor involved in nervous system development and angiogenesis." (PMID 27351129, 2016). "For this, we incubated NRP1-positive BT-474 breast carcinoma cells with NRP1-targeting siRNA in a serum-free medium without transfection reagent and observed the knockdown of the targeted protein." (PMID 27486976, 2016). "Consistently, the expression of NRP1 in human breast cancer tissue negatively correlates with patient survival." (PMID 27351129, 2016). "Overall, our results report that targeting the TMD of NRP1 in breast cancer is a potent new strategy to fight against breast cancer and related metastasis." (PMID 27351129, 2016). "NRP1 promotes breast cancer cell survival and different studies showed a role in cell migration and metastasis." (PMID 27351129, 2016). "A previous report showed that blocking NRP1 function with siRNA or anti-NRP1 antibody treatment decreased mammosphere formation by breast cancer cells in vitro via NF-κB signalling." (PMID 26147006, 2015). "For example, in breast cancer biopsies NRP1 expression is a feature of high-grade tumors, and is frequently expressed in tumors from patients who do not subsequently survive as a result of their cancer." (PMID 25954957, 2015). "These molecules induced apoptosis in NRP-1-expressing breast cancer cells and decreased in vivo tumor growth." (PMID 26090340, 2015). "NRP1 expression was assessed in whole sections of 65 primary breast carcinomas, 95 primary colorectal adenocarcinomas, and 90 primary lung carcinomas." (PMID 24708840, 2014). "Hypo/hyperglycemia also had an impact on VEGFR2 and NRP-1 expression which supports the existence of a possible molecular correlation between type II diabetes mellitus and breast cancer progression." (PMID 25401697, 2014). "A link between NRP-1 expression, NF-κB activation, and mammosphere formation in breast cancer cells has been established." (PMID 23185562, 2012).
breast carcinoma (continued). "Recently, we found that tranilast markedly suppresses Nrp1 expression and NF-κB activation in breast cancer cells." (PMID 22948112, 2012). "Others have reported the expression of syndecans and NRP-1 in these breast cancer cell lines and it is known that these PGs can present CS-GAGs." (PMID 21658254, 2011). "Neuropilin 1 (NRP-1) receptor has been described to be involved in induction of apoptosis in breast cancer cell lines by inhibiting the Akt-signaling pathway." (PMID 20459791, 2010). "The potency and efficacy of the peptide were very similar to previous results from porcine aortic endothelial cells expressing NRP1 and human breast carcinoma MDA-MB-231 cells." (PMID 20087344, 2010). "With regard to NRPs, the expression of NRP-1 mRNA was found to be ubiquitous in all the tested human breast cancer cell lines, whereas NPR-2 mRNA was expressed only by high COX-2 and VEGF-C expressing MDA-MB-231 and Hs578T cells." (PMID 17912247, 2007). "Our findings provide insight into the importance of the VEGF-A/VEGFR2/NRP1 signaling pathway inhibition to improve anti-angiogenic therapy and suggest it could be a promising approach to breast cancer treatment." (PMID 40343434, 2025). "Indeed, SEMA3F uses NRP1 to inhibit E-cadherin and ß-catenin mediated adhesion of breast cancer cells." (PMID 40658724, 2025). "The role of NRP1 has been extensively studied in breast cancer." (PMID 40277760, 2025). "Furthermore, metformin treatment suppressed angiogenesis-related gene expression by downregulating VEGFA, VEGFR2, and NRP1, which highlights its potential to target both apoptotic and angiogenic pathways in breast cancer." (PMID 40343434, 2025). "The quality validation results demonstrated that this is a robust and reliable dataset for exploring the transcriptomic changes in response to NRP1 knockdown across multiple claudin-low breast cancer cell lines on the level of genes or individual transcript variants." (PMID 41326436, 2025). "Interestingly, neuropilin-1 (NRP1), a transmembrane glycoprotein overexpressed in breast cancer cells, attenuates ionizing radiation (IR)-induced apoptotic response by suppressing BCL2 transcription through WTAP-mediated m6A methylation." (PMID 40986143, 2025). "For example, breast cancers with high EGF activity have increased NRP-1." (PMID 39683699, 2024). "Additionally, hypoxia can activate vascular endothelial growth factor receptor 1 (VEGFR1) and neuropilin-1 (NRP1) in monocytes, leading to their chemotaxis towards glioma and breast cancer cells." (PMID 39033204, 2024). "IHC analysis of breast cancer tissues showed that EDNRA positively correlated with NRP1." (PMID 39601333, 2024). "Overexpression of NRP1 in BT-747 breast cancer cells leads to upregulation of the oncogene Tenascin-C and is accompanied by an increase in cellular tumorigenic behavior and downregulated breast cancer resistance protein (BCRP/ABCG2), resulting in enhanced sensitivity to chemotherapy." (PMID 37894289, 2023). "Additionally, it has been confirmed that NRP-1 expression in TNBC is up-regulated compared to other breast cancer subtypes, and NRP-1 can be used as a potential target for TNBC treatment." (PMID 36902076, 2023). "Thus, the FOXO3a-miR-29b/miR-338-VEGF-A/NRP1 axis is suggested to be abnormally regulated and to play a crucial role in the development of breast cancer." (PMID 37965449, 2023). "The likely anti-tumor function of the neuropilin-1 we observed might be breast-cancer-specific and is more in line with the older literature describing its essential role in the initiation of the primary immune response." (PMID 36672243, 2023). "Overexpression of NRP1 has been reported in lung, colorectal, and breast cancer." (PMID 37987362, 2023). "Similarly, a clinical study on breast cancer tumor tissue indicated that NRP-1 concentration was significantly higher in patients with lymph node involvement compared with those without lymph node involvement." (PMID 37175499, 2023).